HMGA2 (high mobility group AT-hook 2)
Diseases named in the same sentence as HMGA2 in open-access papers (continued):
Sharing a sentence is not in itself a finding about the gene and the disease.
ovarian carcinoma (62 papers, 2012 to 2025). A malignant neoplasm originating from the surface ovarian epithelium. "For example, HMGA2 is dysregulated in a wide array of human malignancies, encompassing lung, breast, and ovarian cancers, where its heightened expression is linked to an increased likelihood of cancer advancement." (PMID 38473181, 2024). "For example, in ovarian cancer cases, loss of let-7 expression along with the overexpression of HMGA2 is an indicator of a bad prognosis." (PMID 34721577, 2021). "HMGA2 is aberrantly regulated in a broad range of human cancers, including lung, breast, and ovarian cancers and increased expression of HMGA2 correlates with a higher risk of cancer progression." (PMID 33668453, 2021). "The Let-7/HMGA2 dysregulation is a key factor in ovarian cancerogenesis in distinguishing type I from type II ovarian cancer, Let-7 downregulation being associated with less differentiated ovarian cancers." (PMID 29389895, 2018). "For example, in ovarian cancers, loss of let-7 and up-regulation of HMGA2 are significantly associated with unfavorable prognosis." (PMID 26779370, 2015). "Let-7 is known to regulate several oncogenes, including Ras, c-Myc, and Hmga2, and the repression of let-7 has been linked to several tumor types, such as lung, breast, and ovarian cancer." (PMID 24475120, 2014). "Moreover, Hmga2 is abnormally regulated in various human cancers including lung, breast, and ovarian cancers, and its increased expression is associated with a high risk of cancer progression." (PMID 40182023, 2025). "Considering the key role of ATM (ataxia telangiectasia mutated kinase) in DSB repair, we hypothesized that HMGA2 could regulate ATM to influence the sensitivity to PARPi in ovarian cancer cell." (PMID 32005272, 2020). "Furthermore, HMGA2 overexpression was found to be linked to poor OS in various cancers except ovarian cancer (pooled HR = 1.14; 95% CI = 0.62–2.09; P = 0.673)." (PMID 29416690, 2018). "However, the precise mechanisms underlying HMGA2-mediated promotion of ovarian cancer cell growth processes require elucidation in future studies." (PMID 30474570, 2018). "USP39 promotes efficient splicing of the oncogenic transcription factor HMGA2 at 5’ and 3’ splice sites and increases the malignancy of ovarian cancer cells." (PMID 40990019, 2025). "The frequency of HMGA2 positivity was highest in cancers of the ovary and the endometrium (52.6–92.6%), thyroidal neoplasms (53.4–95%), salivary gland neoplasms (66.7–98%), and non-seminomatous testicular germ cell tumors (73.5–93.5%)." (PMID 40518465, 2025). "Transfection of HMGA2 siRNA has also shown to suppress proliferation and growth of ovarian cancer cells overexpressing HMGA2, and decrease tumor xenografts in athymic nude mice treated with a HMGA2‐targeting construct." (PMID 35388973, 2022). "Combined analysis of RIP-seq and RNA-seq data, we identified USP39 facilitates efficient splicing of HMGA2 and that USP39 exerts oncogenic potential partially through regulating HMGA2 in ovarian cancer cells." (PMID 33731694, 2021). "Previous study found that ATIPs that had a tumour suppressing effect were downregulated in ovarian cancer cells, while the high-mobility group, AT-hook 2 (HMGA2), was overexpressed." (PMID 34539580, 2021). "In particular, USP39 facilitates efficient splicing of HMGA2 and thereby increases the malignancy of ovarian cancer cells." (PMID 33731694, 2021). "Multiple studies have reported that miR-182 enhanced HMGA2 expression and promoted ovarian cancer invasion via direct binding to the SNAIL1 promoter." (PMID 34721577, 2021). "For example, HMGA2 knockdown arrests cells in the G1 phase in ovarian cancer, but in the G2/M phase in leukemia." (PMID 33668453, 2021). "Meanwhile, other studies have reported that HMGA2 was overexpressed in melanoma cancer, ovarian cancer, and nasopharyngeal cancer." (PMID 33519932, 2021).
ovarian carcinoma (continued). "The overexpression of HMGA2 confers a powerful oncogenic signal in ovarian cancers through the modulation of EMT genes." (PMID 34885059, 2021). "Previous research found HMGA2 was over expressed in embryonic tissue and in various malignant tumors such as colorectal, breast, pulmonary and ovary cancer, but was rare detected in normal adult tissues." (PMID 34336701, 2021). "For example, several lines of evidence reported that overexpressed HMGA2 conversely correlates with the expression levels of its regulators let-7 and miR-145, in the ovarian cancer tissues and cell lines." (PMID 32850313, 2020). "Gene silencing therapy using siRNA suppressed proliferation and growth of ovarian cancer cell lines overexpressing HMGA2 by cell cycle arrest at G1 phase, and decreased the size of tumor xenografts in athymic nude mice treated with a Hmga2-targeting construct." (PMID 32365712, 2020). "Above all, these results suggested to us that miR-509-3 mediated Olaparib sensitization by directly impairing HMGA2-ATM axis as well as downregulating RAD51 in ovarian cancer." (PMID 32005272, 2020). "Their study revealed that ovarian cancer patients with high HMGA2 and low let-7 expression in their cancer tissues had lower survival rates than patients with low HMGA2 and high let-7 expression." (PMID 32850313, 2020). "In our previous studies of human endometrial cancer and ovarian cancer cells, we showed that H19 positively regulates HMGA2 expression via the H19/let-7 axis." (PMID 31089260, 2019). "Our results showed that increased expression of miR-219-5p leads to significant reversal of HMGA2-induced cell migration, invasion and proliferation of ovarian cancer cells." (PMID 30474570, 2018). "Let-7 microRNA is downregulated in ovarian cancer and determines an overexpression of HMGA2: HMGA2 is overexpressed in 65% of ovarian cancers, and, particularly, in high-grade serous carcinomas." (PMID 29389895, 2018). "In our experiments, overexpression of HMGA2 reversed miR-219-5p-induced inhibition of ovarian cancer cell proliferation, migration and invasion." (PMID 30474570, 2018). "In conclusion, miR-219-5p inhibits cell proliferation, invasion and migration of ovarian cancer cells through interactions with the 3′-UTR of HMGA2." (PMID 30474570, 2018). "The aim of this study was to investigate the potential involvement of a specific miRNA, miR-219-5p, in HMGA2-induced ovarian cancer." (PMID 30474570, 2018). "The mechanism through which Let-7 favors ovarian cancer tumor progression is related to the capacity of this miRNA to target various oncogenes such as HMGA-2, MYC and K-Ras." (PMID 29389895, 2018). "In the current study, miR-219-5p suppressed the proliferation, migration and invasion of ovarian cancer cells through suppression of HMGA2, both in vitro and in vivo." (PMID 30474570, 2018). "The fact that HMGA2 is not frequently expressed in clear cell carcinomas although this is one of the tumor groups with the lowest expression of the miRNAs, suggests some other type of HMGA2 regulation in at least this ovarian cancer subgroup." (PMID 28423547, 2017). "Altered expression of the high-mobility group AT-hook protein gene, HMGA2, has been reported in both benign and malignant ovarian tumors." (PMID 28423547, 2017). "In order to find new tools to make diagnosis of Epithelial Ovarian Cancer (EOC) at early stages we have analyzed the presence of specific HMGA2 mRNA in the plasma of patients affected by this neoplasm." (PMID 25749380, 2015). "HMGA2 overexpression has been detected in several human malignancies, in particular pancreatic, lung, thyroid, and ovarian cancer representing a very useful biomarker of malignancy." (PMID 25749380, 2015). "The role of HMGA2 in the induction and progression of ovarian cancer has been conclusively demonstrated by a study where HMGA2 was reported to be able to increase proliferation, migration, and metastatic properties of ovarian cancer cells." (PMID 25859543, 2015).
ovarian carcinoma (continued). "The aim of our study has been to evaluate the expression of circulating HMGA2 mRNA in the plasma of patients affected by EOC in order to have a new tool for the early diagnosis of ovarian carcinoma." (PMID 25749380, 2015). "HMGA2 overexpression has been identified in 65% of ovarian carcinoma but are rarely expressed in normal ovarian epithelial cells." (PMID 22235203, 2012). "Additionally, research has identified HMGA2, a protein typically present during fetal development, as being excessively expressed in ovarian cancer cases." (PMID 38473181, 2024). "Gunal reported that hsa-let-7d-3p could downregulate the HMGA2 and KRAS genes and that the loss of hsa-let-7d-3p expression led to the progression of epithelial ovarian cancer related to tumorigenesis, invasion, and metastasis." (PMID 35907902, 2022). "A putative regulatory axis of let-7d, HMGA2 and KRAS may be associated with tumorigenesis, invasion, and metastasis in epithelial ovarian cancer." (PMID 34298978, 2021). "Some researchers have proved that HMGA2 could promote the G1/S and G2/M phase transitions, respectively, in the ovarian cancer and leukemia." (PMID 34513922, 2021). "Activation of RAF-1 increases HMGA2 expression in Pa-4 ovarian cancer cells." (PMID 33668453, 2021). "Recent investigations showed that HMGA2 is significantly overexpressed in most of ovarian cancers." (PMID 34721577, 2021). "Ratio of HMGA2 to let-7 has been discovered as a prognosis factor in ovarian carcinoma patients." (PMID 34721577, 2021). "Importantly, high levels of HMGA2 indicated poor overall survival and progression-free survival of ovarian cancer patients according to the data from the Kaplan–Meier Plotter." (PMID 33731694, 2021). "Furthermore, we measured the relative expression levels of miR-509-3 and HMGA2 in FFPE samples of ovarian cancer patients and concluded that HMGA2 level was negatively correlated with miR-509-3 (Pearson r = − 0.3844, P = 0.01)." (PMID 32005272, 2020). "The transwell assay showed that upregulation of HMGA2 could partially counteract miR-509-3-mediated inhibition on invasion of ovarian cancer cells, which indicated that miR-509-3 inhibited invasion by targeting HMGA2." (PMID 32005272, 2020). "MiR-509-3 could impair the proliferation, migration, and invasion ability but enhance the sensitivity to Olaparib of ovarian cancer cell in vitro and in vivo by directly targeting HMGA2 and RAD51." (PMID 32005272, 2020). "In particular, we could show that IGF2BP1 shields the transcripts of LIN28B and HMGA2 as well as its own mRNA from let-7-mediated downregulation in ovarian cancer-derived cells, thus promoting an aggressive tumor phenotype." (PMID 32545414, 2020). "High levels of HMGA2 are reported in various cancer types, including ovarian cancer." (PMID 30474570, 2018). "The collective results showed that upregulation of miR-219-5p inhibits ovarian cancer growth in vivo, which may be mediated via regulation of HMGA2 levels." (PMID 30474570, 2018). "Transwell migration and invasion assays further showed that upregulation of HMGA2 significantly reverses miR-219-5p-induced inhibition of migration and invasiveness, confirming that HMGA2 is involved in miR-219-5p mediated regulation of ovarian cancer cell growth." (PMID 30474570, 2018). "Data from this investigation clearly suggest that HMGA2 promotes ovarian cancer development." (PMID 30474570, 2018). "The main aim of this investigation was to establish whether miR-219-5p-HMGA2 interactions play a regulatory role in ovarian cancer progression." (PMID 30474570, 2018). "In addition, miR-219-5p was determined as a regulator that inhibits HMGA2 expression in ovarian cancer." (PMID 30474570, 2018). "Since we have previously shown that truncation of HMGA2 is not common in ovarian malignant tumors, we in this study focused on other causes of HMGA2 deregulation analyzing two miRNAs that are known to target HMGA2 and suppress its function, miR-30c and let-7a." (PMID 28423547, 2017).
ovarian carcinoma (continued). "HMGA2 overexpression represents a feature of several malignances including ovarian carcinomas." (PMID 25749380, 2015). "In particular, we have previously shown that HMGA2 overexpression positively correlated with the body mass index suggesting that the combined evaluation of HMGA2 expression and obesity can be considered a marker of poor prognosis in patients affected by ovarian carcinoma." (PMID 25749380, 2015). "Similarly, 5-year progression free survival rate was found to be higher in ovarian cancer patients with lower HMGA2/let-7 ratios compared to those with higher HMGA2/let-7 ratios." (PMID 22479342, 2012). "We then speculated that HMGA2 might increase the oncogenic capacity of ovarian cancer cells." (PMID 33731694, 2021). "Downregulation of HMGA2 could increase the sensitivity to Olaparib in ovarian cancer cells." (PMID 32005272, 2020). "Ectopic expression of HMGA2 can also promote epithelial tumor cell proliferation and metastasis by influencing the cell cycle in a tumor cell-type dependent manner, where, for instance, its knockdown arrests ovarian cancer cells at G1 and G2/M arrest for leukemia cells." (PMID 32365712, 2020). "However, the molecular role of HMGA2 in ovarian carcinoma is yet to be established." (PMID 30474570, 2018). "Specifically, overexpression of HMGA2 was significantly associated with poor prognosis in patients with ccRCC, head and neck cancer, hepatocellular carcinoma and pancreatic ductal adenocarcinoma, but not esophageal adenocarcinoma and ovarian carcinoma." (PMID 29997523, 2018). "Therefore, based on our previous findings that indicated HMGA2 as a promising biomarker for ovarian cancer, the aim of this study has been to investigate whether cell free HMGA2 mRNA could be detected in the peripheral blood of patients with ovarian cancer." (PMID 25749380, 2015). "This suggests that HMGA2 may be a possible target in ovarian cancer therapy." (PMID 22235203, 2012). "Continuous secretion of INAVA‐enriched EVs derived from ovarian cancer cells transfers INAVA mRNA to NOFs within the TME, thereby activating the INAVA/HMGA2/STAT3 axis and promoting NOF activation." (PMID 40265981, 2025). "Increased levels of HMGA2 then binds to the promoter of STAT3 for increased transcription, leading to NOF activation to promote growth and metastasis of ovarian cancer cells." (PMID 40265981, 2025). "Consistently, a positive correlation between HMGA2 and STC2 IHC staining score is also revealed in human epithelial ovarian cancer samples." (PMID 35501821, 2022). "In ovarian cancer, USP39 promotes the proliferation and invasion of cancer cells by facilitating efficient splicing of the oncogenic transcription factor HMGA2." (PMID 35627203, 2022). "miR-509-3 directly targets HMGA2 and RAD51 enhances the sensitivity to Olaparib in ovarian cancer in both in vitro and in vivo experiments." (PMID 33668453, 2021). "We first measured HMGA2 expression in A2780 and CAOV3 ovarian cancer cell lines with USP39 knockdown and in A2780 cells with USP39 overexpression." (PMID 33731694, 2021). "Mechanistically, HMGA1P6 promoted ovarian cancer cell malignancy by acting as a ceRNA (competitive endogenous RNA) that led to enhanced HMGA1 and HMGA2 expression." (PMID 32127525, 2020). "Tumor‐suppressive actions of let‐7 are attributed to its role in suppressing oncogenes and genes involved in maintenance of pluripotency, such as HMGA2 and LIN28A, and let‐7 directly targets these genes in ovarian cancer." (PMID 32652647, 2020). "We next transfected gradient concentration of HMGA1P6 plasmid into ovarian cancer cells and then evaluated HMGA1 and HMGA2 expression." (PMID 32127525, 2020). "The ovarian cancer cell line, SKOV3, was employed, and miR-219-5p and HMGA2 overexpression vectors constructed." (PMID 30474570, 2018). "Expression of miR-219-5p led to suppression of proliferation, invasion and migration of the ovarian cancer cell line, SKOV3, by targeting HMGA2." (PMID 30474570, 2018).
ovarian carcinoma (continued). "High level of HMGA2 could be associated with poor OS in patients with clear cell renal cell carcinoma, head and neck cancer, hepatocellular carcinoma and pancreatic ductal adenocarcinoma, but not esophageal adenocarcinoma and ovarian carcinoma." (PMID 29997523, 2018). "HMGA2 is expressed in embryonic tissues and certain malignant tumours like ovarian cancer but not normal adult tissues." (PMID 35501821, 2022). "The oncogenic features of miR-182 in ovarian cancer are noticeably due to impairment in double-strand breaks repair in DNA, negative control of BRCA1, suppression of metastasis suppressor 1 (MTSS1), and overexpression of high-mobility group AT-hook 2 (HMGA2)." (PMID 34721577, 2021). "In addition, in ovarian cancer, BACH1 boosts the metastasis of cancer cells by enhancing the expressions of Slug, Snail, and HMGA2." (PMID 34191748, 2021). "let-7 suppresses multiple ovarian cancer oncogenes including KRAS, HRAS, c-MYC, and HMGA-2." (PMID 32256980, 2020). "In these conditions, IGF2BP1, LIN28B and HMGA2 form a partially self-sustaining oncogenic triangle, where HMGA2 enhances cell growth, and IGF2BP1 and LIN28B promote the migratory and self-renewal potential of ovarian cancer cells." (PMID 31434359, 2019). "Thus, E-Cadherin, P-Cadherin, Zeb1, HMGA2, Rab25, CD24, NCAM (CD56), Sox11 and Vimentin expression was assessed in 100 advanced-stage ovarian cancer patients undergoing platinum-based chemotherapy." (PMID 29389895, 2018). "Here, we report that HMGA2 specific mRNA was found in 85.1% of the plasma from ovarian cancer patients, but not in the healthy donors, and its detection correlates with the expression of HMGA2 protein in the ovarian carcinoma sections of the same patients." (PMID 25749380, 2015). "Therefore, downregulation of HMGA2 and KRAS by let-7d could exert an anti-oncogenic effect in ovarian cancer." (PMID 34298978, 2021). "The mRNA and protein expression levels in miR-509-3 overexpressing cells and NC cells were assessed by RT-qPCR and Western blot respectively and we found that miR-509-3 could significantly downregulate the mRNA and protein levels of HMGA2 and RAD51 in ovarian cancer cells." (PMID 32005272, 2020). "In addition, HMGA1P6 promotes ovarian cancer aggressiveness through modulating HMGA1 and HMGA2." (PMID 32127525, 2020). "However, in ovarian cancer (pooled HR = 1.14; 95% CI = 0.62–2.09; P = 0.673), HMGA2 overexpression did not prognosticate OS." (PMID 29416690, 2018). "Indeed, it is known that HMGA2 is abundantly expressed in ovarian carcinomas but not in normal ovary tissue." (PMID 25749380, 2015).